REN (renin)
Diseases named in the same sentence as REN in open-access papers (continued):
Sharing a sentence is not in itself a finding about the gene and the disease.
Sepsis (continued). "There was a significant difference in renin concentration between sepsis and septic shock patients on the first (45.8 and 103.4 pg/mL, respectively) and third (24.7 and 102.1 pg/mL, respectively) days, but not on the fifth day (18.9 and 58.6 pg/mL, respectively)." (PMID 36012398, 2022). "This study is the first reporting a positive hemodynamic impact of APLN-13 infusion in a large animal model of septic shock and revealing simultaneous intricate homeostatic disturbances among the renin-angiotensin, kallikrein-kinin, and apelin systems involved in outcomes of acute human sepsis." (PMID 34815457, 2021). "The renin-angiotensin system plays a complex role in the pathophysiology of sepsis." (PMID 24310803, 2013). "Furthermore renin–angiotensin system is disrupted, since the highest concentrations of angiotensin-converting enzyme are localized in the proximal tubular brush border, which is typically dysfunctional during sepsis." (PMID 39985720, 2025). "The ongoing DARK-Sepsis trial (ClinicalTrials.gov NCT05824767) is designed to examine whether baseline renin and DPP3 levels can predict response to angiotensin II therapy compared with standard vasopressor management in patients with vasodilatory shock requiring norepinephrine." (PMID 41226854, 2025). "Renin and dipeptidyl peptidase 3 (DPP3) are components of the renin–angiotensin–aldosterone system which have been shown to outperform lactate in predicting sepsis prognosis, and preliminary data suggest they could prove useful as biomarkers to guide AT2 use in septic shock." (PMID 38475822, 2024). "Cardiorenal and immune disorders could be positively modulated by renin–angiotensin–aldosterone system inhibition in stabilized sepsis-survivors at ICU discharge with potentially a reduction in the progression of organ dysfunction and an improvement in long-term outcomes." (PMID 35449071, 2022). "The incubation of leukocytes with renin induces the production of pro-inflammatory cytokines, including IL-6, and administration of a renin receptor blocker reduced the pro-inflammatory response and increased survival in a rodent model of sepsis induced by cecal ligation and puncture (CLP)." (PMID 36117167, 2022). "Excessive activation of the renin-angiotensin system might further worsen the outcomes of sepsis." (PMID 34836493, 2021). "In this study, as a significantly upregulated gene, MME (membrane metalloendopeptidase) might play an important role in the prognosis of septic shock through the renin-angiotensin system pathway, which is activated to increase the arterial blood pressure in sepsis." (PMID 34836493, 2021). "(d) increased renin-angiotensin system activation may confer hemodynamic advantages in sepsis." (PMID 33123579, 2020). "In the sepsis group, the higher β2-AR expression in the glomerulosa suggested a role for mineralocorticoid synthesis and secretion, related to compensatory mechanisms activated to increase volemia and arterial blood pressure through the renin–angiotensin–aldosterone system (RAAS)." (PMID 31234562, 2019). "In the search for these mechanisms, our previous research suggested an impact of a decreased AQP5 expression in C-allele carriers on sepsis survival via its influence on the renin–angiotensin–aldosterone system, which however could not be confirmed." (PMID 27871297, 2016). "In addition, sepsis could activate the renin-angiotensin-aldosterone system (RAAS) in renal sympathetic and angiotensin activities, which leads to vasoconstriction in patients with sodium and water retention." (PMID 25886952, 2015). "There is an increasing amount of data indicating that renin is a better marker of tissue hypoperfusion and predictor of intensive care unit (ICU) mortality in patients with sepsis and septic shock, even outperforming lactate." (PMID 40880376, 2025). "This shift in patient population is better positioned to establish a clear connection between renin and the ARDS progression in sepsis patients." (PMID 38509149, 2024).
Sepsis (continued). "Ein Beispiel für den Einsatz von einem einfachen Biomarker zur Subphänotypisierung mit potenziell direkter therapeutischer Konsequenz ist die Sepsis-assoziierte AKI, wo Störungen im Renin-Angiotensin-Aldosteron-System eine wichtige Rolle spielen." (PMID 38683229, 2024). "Renin has been identified as a biomarker of major adverse kidney events, AKI in cardiac surgery and sepsis, and impaired tissue perfusion in critically ill adults with septic shock." (PMID 37842390, 2023). "Collectively, these data suggest that renin and DPP3 warrant additional prospective study as biomarkers in sepsis and specifically as biomarkers that may identify patients likely to benefit from AT2 therapy." (PMID 38475822, 2024). "There was a significant difference in renin concentration between sepsis survivors and non-survivors on the third (31.5 and 119.9 pg/mL, respectively) and fifth (18.2 and 106.7 pg/mL, respectively) days." (PMID 36012398, 2022). "Therefore, when sepsis develops, the careful monitoring of potential AKI development is recommended in patients using renin–angiotensin–aldosterone system inhibitors." (PMID 30039479, 2018). "The renin-angiotensin system (RAS) affects the microvasculature, yet the relationships between RAS and organ injury in clinical sepsis remain unclear." (PMID 20175923, 2010). "There was a significant difference in renin concentration between sepsis survivors and non-survivors on the third (31.5 and 119.9 pg/mL, respectively) and fifth (18.2 and 106.7 pg/mL, respectively) days, but not on the first day (75.1 and 102.1 pg/mL, respectively)." (PMID 36012398, 2022). "TIMP-1 (p=0.083) and renin (p=0.12) showed a non-significant decrease in response to combined (GENT and PTX) treatment compared to untreated sepsis." (PMID 39963236, 2024). "As of March 8th, 2023, a PubMed search of “Renin, Sepsis, ARDS, Mortality” yields 8 results, 4 of which were within the last year, and none of which assayed for renin level." (PMID 38509149, 2024). "Plasma renin activity has not been found to correlate with mean arterial pressure (MAP), preventing the claim that arterial pressure is the main contributor to activated RAAS in sepsis." (PMID 36012398, 2022). "In the context of sepsis, arterial underfilling arising from systemic inflammation-induced arterial vasodilation serves as a robust trigger for the activation of the sympathetic nervous system (SNS), the renin–angiotensin–aldosterone axis (RAAS), and the non-osmotic release of vasopressin (AVP)." (PMID 38799155, 2024).
renovascular hypertension (52 papers, 2013 to 2025). High blood pressure secondary to renal artery stenosis. "The current mostly accepted mechanism for renovascular hypertension is that a reduction in blood flow perfusion to the kidney causes alterations in the renin‒angiotensin‒aldosterone system." (PMID 39439670, 2024). "Renovascular hypertension in the 2K-1C model is initially induced by renin secretion stimulation caused by decreased renal perfusion, leading to increased systemic Ang II concentration." (PMID 34177612, 2021). "Studies in pig models with unilateral RAS show that in early renovascular hypertension, an increase in plasma renin activity and arterial pressure is associated with rising markers of oxidative stress—predominantly isoprostanes." (PMID 34070611, 2021). "Renovascular hypertension is a type of secondary hypertension caused by renal artery stenosis, leading to an increase in the renin–angiotensin–aldosterone system (RAAS)." (PMID 34113255, 2021). "Transplant renal artery dissection is a rare and serious event that can cause allograft dysfunction and activation of the renin–mediated renovascular hypertension." (PMID 31996160, 2020). "Transplant renal artery dissection (TRAD) is a rare and serious event that can cause allograft dysfunction and activation of the renin–mediated renovascular hypertension." (PMID 31996160, 2020). "Among the different types of high BP, renovascular hypertension is an important cause of secondary hypertension, which is characterized by increased activation of the renin-angiotensin system (RAS)." (PMID 25223948, 2014). "Depending on the severity, extent, and main artery versus branch involvement, SRAD may cause renal ischemia of varying degree, renin-mediated renovascular hypertension, and renal infarction." (PMID 26090259, 2015). "This persistent increase in plasma renin activity in db RAS mice may reflect interactions between hemodynamic forces associated with renovascular hypertension and the diabetic mileau." (PMID 24708836, 2014). "In contrast to our patient’s suppressed aldosterone and renin levels, renovascular hypertension generally exhibits elevated renin and aldosterone due to impaired renal perfusion." (PMID 39498427, 2024). "Significantly higher concentration of ADM was observed in malignant and renovascular hypertension, suggesting a potential contribution of the renin–angiotensin system (RAS) activation in the elevation of ADM levels." (PMID 38069140, 2023). "In a previous study, NaHS significantly decreased renin activity in the two-kidney-one-clip (2K1C) model of renovascular hypertension." (PMID 36675205, 2023). "Experimental observations showed that renovascular hypertension was mainly maintained by the renin–angiotensin–aldosterone system (RAAS)." (PMID 37658182, 2023). "H2S has been reported to inhibit the activity of renin by reducing the synthesis and release of renin, which has potential therapeutic value for renovascular hypertension." (PMID 36219347, 2022). "The increase in renin–angiotensin–aldosterone system (RAAS) activity has a pivotal role in the development of renovascular hypertension." (PMID 34113255, 2021). "It is well accepted that the initial phase of the renovascular hypertension is mediated by the renin-angiotensin system (RAS) and occurs in approximately 4 weeks after clipping the kidney." (PMID 33145109, 2020). "It has been reported that H2S treatment inhibited the upregulation of renin level in renovascular hypertensive rats accompanying with a reduction of intracellular cAMP level in primary cultures of renin-rich kidney cells." (PMID 31390847, 2019). "Vasoconstriction is primarily mediated through renin-angiotensin-aldosterone axis activation and increased sympathetic activity in renovascular hypertension." (PMID 31053874, 2019).
renovascular hypertension (continued). "From the previous studies it has been observed that the development of renovascular hypertension depends on the release of renin from the juxtaglomerular (JG) cells, a process regulated by intracellular cAMP." (PMID 26221579, 2015). "In the mouse model, the few available studies have reported an increase in renin activity and the levels of Ang I (~50%), Ang II (~350%) and Ang 1–7 in plasma (~110%) during the first phase of renovascular hypertension (14 days following the clip placement)." (PMID 25223948, 2014). "Db/db mice with renovascular hypertension developed greater and more prolonged elevation of renin activity than all other groups studied." (PMID 24708836, 2014). "Secondary hyperaldosteronism (SAL) results from overactivation of the renin-angiotensin system (RAS) and is therefore characterised by elevated aldosterone and renin levels and usually occurs in adults with renovascular hypertension or renin-secreting tumours." (PMID 25276129, 2014). "The 2K1C renovascular hypertension is a classic animal model of renin-dependent hypertension, which is considered to be similar to human renal hypertension." (PMID 24447776, 2014). "Renovascular hypertension results in decreased blood flow to the kidney, resulting in increased production of renin." (PMID 24678641, 2014). "In experimental renovascular hypertension with preserved kidney mass (2K1C), the renin-angiotensin-aldosterone system (RAAS) is found to be activated, and central nervous system effects of angiotensin II probably are the driving force of sympathoactivation." (PMID 24946879, 2014). "The pathophysiology of renovascular hypertension, involves increased activation of the renin-angiotensin axis." (PMID 23531087, 2013). "Activation of the renin-angiotensin-aldosterone system plays a critical role in the development of chronic renal damage in patients with renovascular hypertension." (PMID 24025423, 2013). "Based on these considerations, we propose that intra-renal activation of the renin-angiotensin system plays an important role in the development of renovascular hypertension." (PMID 24025423, 2013). "To study the NO/cGMP signaling under pathophysiological conditions, we challenged the NO-GC1 KO mice by the 2K1C operation which provokes renovascular hypertension by activation of the renin-angiotensin system." (PMID 24260450, 2013). "Examination of biochemical markers of hyperreninemic hyperaldosteronism such as serum renin concentrations and/or urinary potassium concentrations may have been a useful adjunct in confirming the diagnosis of renovascular hypertension." (PMID 39875455, 2025). "In addition, renovascular hypertension is a known complication of traumatic renal artery injury; this is due to the activation of the renin-angiotensin system in response to poor renal perfusion." (PMID 41306177, 2025). "Besides volume and salt overload, the renin-angiotensin system (RAS) plays a major role in the development of renovascular hypertension." (PMID 36996194, 2023). "On the other hand, as the renovascular hypertension model used in our study (2K1C) induces a sustained activation of the renin-angiotensin system (RAS), we chose another classic drug (ENAL) capable of effectively blocking activation and preventing the installation of renovascular hypertension." (PMID 29234376, 2017). "There is a possibility that allicin may act through another mechanism, specifically through the inhibition of the renin-angiotensin system which plays a significant role in renovascular hypertension." (PMID 27990229, 2016). "In addition, ACE was increased in the unclipped kidney while renin was elevated in the clipped kidney confirming previous findings of the RAS in animals with renovascular hypertension." (PMID 25706121, 2015). "In conclusion, these results demonstrate that H2S may inhibit renin activity by decreasing the synthesis and release of renin, suggesting its potential therapeutic value for renovascular hypertension." (PMID 26221579, 2015).
renovascular hypertension (continued). "Moreover, H2S is found to inhibit renin release in rat models of renovascular hypertension." (PMID 35743160, 2022). "Even when renin activity returns to normal, arterial pressure remains elevated along with isoprostrane levels, possibly due to a prolonged effect of angiotension II within the ischaemic tissue, demonstrating a correlation between renovascular hypertension and oxidative stress." (PMID 34070611, 2021). "However, the brain “ouabain” and/or the brain renin-angiotensin system may become pertinent for sympathoactivation in renovascular hypertension with reduced kidney mass possibly through a sodium-dependent mechanism." (PMID 24946879, 2014). "Renal artery stenosis (RAS) reduces renal blood flow and activates the renin‐angiotensin‐aldosterone (RAA) system, resulting in renovascular hypertension (RVH)." (PMID 40909303, 2025). "Postmenopausal women exhibit an increase in plasma renin activity, suggesting activation of the RAS similarly to what occurs during renovascular hypertension." (PMID 29234376, 2017). "While juxtaglomerular renin is upregulated in the clipped kidney and downregulated in the non-clipped kidney, in the experimental model of reno-vascular hypertension, renin in the collecting duct is upregulated in both non-clipped and clipped kidneys." (PMID 39337535, 2024).
coronary artery disease (51 papers, 2008 to 2026). "The case-control study from Iran investigated the relationship between six gene polymorphisms of renin-angiotensin system compound components and coronary disease." (PMID 38021526, 2023). "Several polymorphisms within the renin-angiotensin system cluster of genes have been associated with the advent of coronary artery disease (CAD) or related pathologies." (PMID 18637188, 2008). "As an anti-inflammatory, butyrate-producing bacterium, Subdoligranulum has been found to be depleted in patients with coronary artery disease, and is probably implicated in blood pressure regulation via vascular function, inflammation reduction, and renin–angiotensin system modulation." (PMID 40732909, 2025). "A recent study showed that the mRNA expression of GLP-1R was considerably associated with the components of the renin-angiotensin-aldosterone system (RAAS) detected in epicardial and pericardial fat in patients with severe coronary artery disease." (PMID 36865917, 2023). "In this study, we found that there was lower medication rate of renin-angiotensin blockers in elderly coronary artery disease patients with reduced left ventricular ejection fraction (LVEF) or those with cardiac sudden death." (PMID 34606471, 2021). "The study of the genotype distribution for REN rs41317140 revealed a significant difference between the control group and the patients with coronary artery disease." (PMID 34065198, 2021). "It was also observed that vitamin D inhibited the intracellular NF-κB pathway and in vitro renin synthesis and attenuated the progression of coronary artery disease." (PMID 33425213, 2020). "Changes in cardiovascular disease in ADPKD are uncertain but may related to use of anti-hypertensive agents including renin angiotensin blockade and paradoxical increase in coronary artery disease due to longer survival on KRT, but data to support this are lacking." (PMID 41023960, 2025). "DM II sustaines the development of coronary artery disease (CAD), as well as insulin resistance, glucose toxicity, vascular and microcirculatory dysfunction, inflammation and the activation of the renin–angiotensin–aldosterone system (RAAS)." (PMID 38337436, 2024). "However, we should monitor the adverse effects of renin-angiotensin blocker and ARNI in the elderly coronary artery disease patients, especially when accompanying with prerenal hypoperfusion or combined medication of aldosterone receptor antagonists." (PMID 34606471, 2021). "However, the role of plasma prorenin and renin in the development and progression of coronary artery disease (CAD) is still not clear." (PMID 26167285, 2015).